RN7SL100P (RNA, 7SL, cytoplasmic 100, pseudogene)
Gene: Miscellaneous RNA gene on chromosome 9 (26,895,678 to 26,895,970, forward strand). Ensembl gene ENSG00000240306.
Homologues: Orthologues: chimpanzee Metazoa_SRP (99% identical), macaque Metazoa_SRP (80% identical). Paralogues in human: RN7SL2 (69% identical), RN7SL1 (68% identical), RN7SL554P (68% identical), RN7SL3 (67% identical), RN7SL509P (67% identical), RN7SL607P (67% identical), RN7SL234P (67% identical), RN7SL543P (67% identical), RN7SL5P (67% identical), RN7SL33P (67% identical), RN7SL448P (67% identical), RN7SL300P (66% identical), and 700 more.